MARCHF8 (membrane associated ring-CH-type finger 8)
Description:
E3 ubiquitin-protein ligase that plays several important roles in innate immunity and adaptive immunity. Mediates ubiquitination of CD86 and MHC class II proteins, such as HLA-DR alpha and beta, and promotes their subsequent endocytosis and sorting to lysosomes via multivesicular bodies. Possesses a very broad antiviral activity by specifically inactivating different viral fusion proteins. Targets and ubiquitinates cytoplasmic lysine residues of viral envelope glycoproteins with single transmembrane domains leading to their lysosomal degradation. Therefore, shows broad-spectrum inhibition against many viruses including retroviruses, rhabdoviruses, arenaviruses, sarbecoviruses or influenzaviruses. Strongly blocks human immunodeficiency virus type 1 envelope glycoprotein incorporation into virions by down-regulating its cell surface expression. Also blocks ebola virus glycoprotein/GP incorporation via surface down-regulation. Mediates 'Lys-63'-linked polyubiquitination of influenza M2 to target it to lysosome for degradation. Mediates the regulation of constitutive ubiquitination and trafficking of the viral restriction factor BST2 within the endocytic pathway. Plays a role in maintenance of immune tolerance to self by promoting the turnover and proteasomal degradation of PD-L1/CD274 via ubiquitination. Catalyzes the 'Lys-63'-linked polyubiquitylation of cGAS thereby inhibiting its DNA binding ability and impairing its antiviral innate immunity. Negatively regulates IL7-mediated T-cell homeostasis by mediating 'Lys-27'-linked polyubiquitination of IL7R, leading to its lysosomal degradation. (Microbial infection) Mediates 'Lys-63'-linked polyubiquitination of hepatitis C virus/HCV protein NS2 which allows its binding to HGS, an ESCRT-0 complex component, and this interaction is essential for HCV envelopment.
Synonyms: c-MIR; MARCH-VIII; MARCH8; MIR; RNF178; CMIR
Tractability: Antibody: UniProt predicts a signal peptide or a membrane-spanning region.
Gene: Protein-coding gene on chromosome 10 (45,454,585 to 45,594,931, reverse strand). Ensembl gene ENSG00000165406.
Subcellular location: Golgi apparatus membrane; Endoplasmic reticulum membrane; Cytoplasmic vesicle membrane; Lysosome membrane; Early endosome membrane
Gene Ontology:
Molecular function: protein binding; ubiquitin protein ligase activity; ubiquitin-protein transferase activity; MHC protein binding; zinc ion binding
Biological process: proteasome-mediated ubiquitin-dependent protein catabolic process; protein polyubiquitination; antigen processing and presentation of peptide antigen via MHC class II; immune response; protein ubiquitination
Cellular component: cytoplasmic vesicle membrane; early endosome membrane; endoplasmic reticulum membrane; endosome; Golgi membrane; lysosomal membrane; lysosome; cytoplasm; host cell plasma membrane; late endosome membrane
Genetic constraint (gnomAD): Loss-of-function variants: 39 observed, 50.88 expected, observed/expected ratio (o/e) 0.77, 90% interval 0.59 to 1. The upper end of that interval is the gene's LOEUF score, 1, which puts it in group 4 of 6, group 1 being the genes least tolerant of losing a copy. Missense variants: 685 observed, 729.62 expected, observed/expected ratio (o/e) 0.94, 90% interval 0.88 to 1. Synonymous variants: 263 observed, 285.2 expected, observed/expected ratio (o/e) 0.92, 90% interval 0.83 to 1.02.
Homologues: Orthologues: chimpanzee MARCHF8 (98% identical), macaque MARCHF8 (97% identical), pig MARCHF8 (88% identical), dog MARCHF8 (83% identical), rat Marchf8 (83% identical), mouse Marchf8 (83% identical), rabbit MARCHF8 (81% identical), tropical clawed frog marchf8 (63% identical), guinea pig Marchf8 (45% identical), zebrafish marchf8 (40% identical), Drosophila melanogaster CG4080 (20% identical). Paralogues in human: MARCHF1 (41% identical), MARCHF4 (13% identical), MARCHF11 (12% identical), MARCHF9 (12% identical), MARCHF2 (10% identical), MARCHF3 (10% identical).
Diseases named in the same sentence as MARCHF8 in open-access papers:
MARCHF8 is named in the same sentence as 53 diseases in open-access papers, as found by Europe PMC text mining. Sharing a sentence is not in itself a finding about the gene and the disease. The quoted sentences say what the papers report.
viral infection (15 papers, 2019 to 2025). "Furthermore, in future experiments, reintroducing MARCHF8 or NDP52 after knockout may help us quickly determine the role of MARCHF8 or NDP52 in viral infection and may promote the inhibition of SADS-CoV replication by BST2." (PMID 40871369, 2025).
breast carcinoma (10 papers, 2017 to 2025). "In addition, MARCHF8 overexpression also promotes apoptosis and hinders tumorigenesis and metastasis of breast cancer cells by downregulating CD44 and STAT3." (PMID 36867660, 2023). "In addition, MARCHF8 ubiquitinates TRAIL-R1 and decreases apoptosis in gastric and breast cancer cells, and silencing of MARCHF8 induces apoptosis and suppresses cell proliferation, invasion, and migration of cancer cells." (PMID 36867660, 2023). "Interestingly, MARCHF8 ubiquitinates TRAIL-R1 and diminishes its cell surface expression on breast cancer cells." (PMID 36867660, 2023).
esophageal cancer (4 papers, 2017 to 2025). A primary or metastatic malignant neoplasm involving the esophagus. "It has been discovered that MARCHF8 expression is upregulated in gastric and esophageal cancer, and that its expression is associated with poor prognosis." (PMID 36867660, 2023).
head and neck cancer (4 papers, 2023 to 2026). A primary or metastatic malignant neoplasm affecting the head and neck. "Our recent study has shown that the human papillomavirus (HPV) oncoproteins induce MHC-I protein ubiquitination by membrane-associated Ring-CH-type finger 8 (MARCHF8) in HPV-positive head and neck cancer (HPV+ HNC)." (PMID 41889855, 2026). "We report here that membrane-associated RING-CH-type finger 8 (MARCHF8), upregulated by human papillomavirus (HPV), ubiquitinates and degrades MHC-I in HPV-positive head and neck cancer (HPV+ HNC)." (PMID 41802050, 2026). "Here, we report that HPV induces expression of the membrane-associated ubiquitin ligase MARCHF8, which is upregulated in HPV-positive head and neck cancer." (PMID 36867660, 2023). "We have recently demonstrated that HPV16 upregulates MARCHF8 expression in HPV-positive keratinocytes and head and neck cancer (HPV+ HNC) cells." (PMID 38226814, 2024). "Here, we report that MARCHF8 expression is upregulated in HPV-positive head and neck cancer (HNC) patients but not in HPV-negative HNC patients compared to normal individuals." (PMID 36867660, 2023).
esophageal squamous cell carcinoma (3 papers, 2017 to 2024). Esophageal squamous cell carcinoma (ESCC) is a type of esophageal carcinoma (EC) that can affect any part of the esophagus, but is usually located in the upper or middle third. "A recent study showed that membrane-associated ring-CH-type finger 8 (MARCHF8) knockdown in esophageal squamous cell carcinoma cells increases the levels of CUL1 and UBE2L3 proteins." (PMID 38226814, 2024). "By analyzing proteomics data from a previous study in esophageal squamous cell carcinoma, we found that the CUL1 and UBE2L3 proteins are among the cellular proteins increased by the MARCHF8 knockdown." (PMID 38226814, 2024).
dengue (2 papers, 2021 to 2024). "Likewise, recent studies have shown that MARCHF8 supports infection of several human viruses, including HCV, dengue, and Zika." (PMID 38226814, 2024).
oral cancer (2 papers, 2023 to 2024). "The results from the mouse oral cancer cells were consistent with those from human HNC cells showing a significant increase in MARCHF8 protein levels and a decrease in FAS, TRAIL-R1, and TRAIL-R2 protein levels in mEERL cells compared to NiMOE cells." (PMID 36867660, 2023). "Further, MARCHF8 knockout in mouse oral cancer cells expressing HPV16 E6 and E7 augments cancer cell apoptosis and suppresses tumor growth in vivo." (PMID 36867660, 2023). "We further revealed that downregulation of the death receptors by MARCHF8 prevents cancer cell apoptosis and that knockout of MARCHF8 expression significantly inhibits in vivo tumor growth and enhances tumor-free survival of mice transplanted with mouse oral cancer cells expressing HPV16 E6 and E7." (PMID 36867660, 2023).
lupus (1 paper, 2024). "Among the top four IIT genes per quadrant are several gene products that have previously been shown in other studies to be involved in lupus and/or lymphoma, including Membrane Associated Ring-CH-Type Finger 8 (MARCH8; Quad IV)." (PMID 39336806, 2024).
lymphoma (1 paper, 2024). A malignant (clonal) proliferation of B- lymphocytes or T- lymphocytes which involves the lymph nodes, bone marrow and/or extranodal sites. "Membrane Associated Ring-CH-Type Finger 8 (MARCH8; C−A+ quadrant) plays a regulatory role in lymphoma by downregulating CD98, which promotes proliferation and cell division in lymphomas." (PMID 39336806, 2024).
infection (23 papers, 2010 to 2025). The state of being infected such as from the introduction of a foreign agent such as serum, vaccine, antigenic substance or organism. "MARCHF8 targets several viral envelope glycoproteins to inhibit infections of HIV, vesicular stomatitis virus, rabies virus, lymphocytic choriomeningitis virus, severe acute respiratory syndrome coronavirus (SARS-CoV), chikungunya virus, and Ross River virus (70, –, 72)." (PMID 38226814, 2024). "Thus, our study places MARCHF8 within a larger, orchestrated response to control HSV-1, which acts to protect the host from damage both through infection and inflammation." (PMID 40780411, 2025).
cancer (15 papers, 2014 to 2025). A tumor composed of atypical neoplastic, often pleomorphic cells that invade other tissues. "However, the role of MARCHF8 in HPV-associated cancers is largely elusive despite its importance in regulating immune and death receptors." (PMID 36867660, 2023). "Our results suggest that MARCHF8 is a potent tumor promoter that plays an important role in cancer progression by inducing the degradation of the TNFRSF death receptors and blocking cell apoptosis." (PMID 36867660, 2023). "As E7 is required for HPV replication and carcinogenesis, destabilizing E7 proteins by targeting MARCHF8 may effectively prevent and treat HPV-associated cancers." (PMID 38226814, 2024). "Together, these results suggest that MARCHF8, as a tumor promoter, could be a potential target for cancer therapy to induce cancer cell apoptosis and antitumor immune responses." (PMID 36867660, 2023). "MARCHF8 knockout restores CUL1 and UBE2L3 expression, decreasing E7 protein levels and inhibiting the proliferation of HPV-positive cancer cells." (PMID 38226814, 2024). "Despite these protumor functions in several cancers, including HPV+ HNC, some studies have shown the potential antitumor activity of MARCHF8." (PMID 36867660, 2023).
tumor (13 papers, 2016 to 2026). "In contrast, only two out of ten mice, each injected with either of two mEERL/Marchf8-/- cell lines, showed robust tumor growth and died 8 weeks post injection." (PMID 36867660, 2023). "Our study shows that MARCHF8 knockout dramatically suppresses tumor growth in vivo." (PMID 36867660, 2023). "Inhibiting MARCHF8 restores MHC-I levels on HPV+ HNC cells, suppresses tumor growth, and increases the infiltration of natural killer (NK) and T cells in the tumor microenvironment." (PMID 41802050, 2026). "Knockdown and knockout of MARCHF8 expression in human and mouse HPV+ HNC cells significantly enhances apoptosis and attenuates in vivo tumor growth." (PMID 36867660, 2023). "Additionally, we have recently shown that MARCHF8 ubiquitinates and degrades death receptors to impede apoptosis of HPV+ HNC cells and that MARCHF8 knockout significantly suppresses tumor growth in vivo." (PMID 38226814, 2024). "Further, no tumor formation was observed in three and one mice injected with mEERL/Marchf8-/- cell lines, sgR-Marchf8-2 and sgR-Marchf8-3, respectively, over 12 weeks post injection." (PMID 36867660, 2023). "To determine whether Marchf8 knockout in HPV+ HNC suppresses tumor growth in vivo, we injected syngeneic C57BL/6J mice subcutaneously with either of two 5 X 105 of mEERL/Marchf8-/- cell lines or mEERL/scr cells into the flank." (PMID 36867660, 2023).
MARCHF8 also shares sentences with these, for which no sentence is quoted: HIV-1 infection (13 papers); hepatocellular carcinoma (4); gastric cancer (3); glioma (3); non-small cell lung carcinoma (3); lung adenocarcinoma (2); lung carcinoma (2); lung squamous cell carcinoma (2); melanoma (2); pancreatic cancer (2); Zika (2); Arthritis (1); atherosclerosis (1); breast invasive carcinoma (1); breast tumors (1); cholelithiasis (1); colitis (1); colon adenocarcinoma (1); colorectal cancer (1); diabetes (1); diffuse large B-cell lymphoma (1); digestive system cancer (1); digestive system tumor (1); esophageal tumor (1); experimental autoimmune encephalomyelitis (1); gallstones (1); head and neck squamous cell carcinoma (1); immune dysfunction (1); infectious disease (1); inflammatory bowel disease (1).
A further 11 diseases each share a sentence with MARCHF8 in 1 paper.